LINC-PINT (long independently transcribed non-coding RNA, p53 induced transcript)
Description:
Enhances the binding of the PAF1 complex to target gene promoters and plays a role in negative regulation of transcription. May function as an anchor to keep the PAF1 complex on target gene promoters, sequentially pausing RNA polymerase II-induced mRNA elongation. Inhibits FOXM1-mediated transcription of PHB2.
Synonyms: PINT; TISPL; FLJ43663; PINT87aa; LOC646329; LincRNA-Pint; MKLN1-AS1
Gene: Long non-coding RNA gene on chromosome 7 (130,791,264 to 131,110,176, reverse strand). Ensembl gene ENSG00000231721.
Subcellular location: Nucleus
Gene Ontology:
Biological process: miRNA-mediated post-transcriptional gene silencing
Cellular component: RISC complex
Diseases named in the same sentence as LINC-PINT in open-access papers:
LINC-PINT is named in the same sentence as 85 diseases in open-access papers, as found by Europe PMC text mining. Sharing a sentence is not in itself a finding about the gene and the disease. The quoted sentences say what the papers report.
glioblastoma (11 papers, 2018 to 2025). The most malignant astrocytic tumor (WHO grade IV). "LINC‐PINT is involved in various cancers, such as gastric cancer, glioblastoma, and acute lymphoblastic leukemia." (PMID 31981466, 2020). "But to date, the relevance and underlying mechanisms of LINC-PINT in glioblastoma have not been explored yet." (PMID 33505307, 2020). "However, the relevance and underlying mechanisms of LINC-PINT in glioblastoma have not been explored yet." (PMID 33505307, 2020). "Our findings showed a novel regulation mechanism of LINC-PINT/Wnt signaling/EMT axis in GBM, providing new perspectives into the pathogenesis and invasiveness of glioblastoma and verifying LINC-PINT as a potential prognostic biomarker and novel therapeutic target in GBM." (PMID 33505307, 2020). "Moreover, primary glioblastoma showed higher expression level of LINC-PINT than recurrent group and LGG showed higher expression level of LINC-PINT than GBM group, indicating that LINC-PINT might act as a tumor suppressor in GBM." (PMID 33505307, 2020).
gastric cancer (9 papers, 2018 to 2025). A primary or metastatic malignant neoplasm involving the stomach. "For example, in gastric cancer, upregulated LINC-PINT can inhibit the HIF-α pathway, thereby impeding cancer cell proliferation." (PMID 38553526, 2024). "Interestingly, in osteosarcoma and gastric cancer, LINC-PINT inhibits cell invasion, migration, and proliferation by downregulating miR-21." (PMID 32260415, 2020).
glioma (8 papers, 2018 to 2024). A benign or malignant brain and spinal cord tumor that arises from glial cells (astrocytes, oligodendrocytes, ependymal cells). "Then we carried out gain and loss assay of LINC-PINT to further explore the biological functions of LINC-PINT in glioma." (PMID 33505307, 2020). "To elucidate the mechanism of how LINC-PINT regulates EMT in glioma, we further focused on Wnt/β-catenin signaling." (PMID 33505307, 2020). "When Twist1 is methylated by SETD6 (a methyltransferase), it will increase the occupancy of EZH2 (a histone lysine methyltransferase) and the catalysis of the repressive H3K27Me3 (histone H3 lysine 27 trimethylation) mark at the locus of lncRNA LINC-PINT (a tumor repressor in gliomas)." (PMID 36338770, 2022). "LINC-PINT expression demonstrated a positive correlation with MSI in THCA, SKCM, PRAD, LUSC, LUAD, Lower Grade Glioma (LGG), HNSC, and BRCA (correlation coefficient > 0, P < 0.05)." (PMID 38553526, 2024). "To date, several circRNAs have been reported to play crucial roles in gliomas, such as circ-SMARCA5, circ-MMP9, circ-NT5E, circ-TTBK2, and circ-LINC-PINT." (PMID 31905344, 2020).
colorectal cancer (7 papers, 2017 to 2025). A primary or metastatic malignant neoplasm that affects the colon or rectum. "We also observed that the expression of LINC-PINT is decreased in tumor tissue when compared to normal tissue in independent cohorts of patients of colorectal cancer." (PMID 29078818, 2017). "Moreover, the expression of LINC-PINT in colorectal cancer cell lines is further decreased when cells undergo several passages as tumor xenografts and acquire an aggressive phenotype." (PMID 29078818, 2017). "ROC curve analysis indicated sensitivity and specificity in LINC-PINT and BACE1 for colorectal cancer diagnosis." (PMID 36087249, 2022). "In this study, we have shown a new link between lymph node involvement in patients with colorectal cancer and the levels of LINC-PINT and BACE1 mRNA expression in CRC tumour samples." (PMID 36087249, 2022).
hepatocellular carcinoma (7 papers, 2020 to 2025). A malignant tumor that arises from hepatocytes. "Overexpression of the peptide encoded by LINC-PINT decreases the mitophagy of hepatocellular carcinoma in vitro and in vivo." (PMID 38218807, 2024). "In hepatocellular carcinoma, Xiang and colleagues demonstrated the cancer-inhibitory activity of PINT87aa embedded in lncRNA LINC-PINT depending on its suppression of FOXM1-mediated PHB2." (PMID 38351332, 2024). "PINT87aa, encoded by LINC-PINT, has been found to be overexpressed in senescent hepatocellular carcinoma cells and to arrest the cell cycle, induce cellular senescence and inhibit mitochondrial autophagy, providing evidence for is potential use as a therapeutic target for HCC." (PMID 38622617, 2024).
lung carcinoma (7 papers, 2017 to 2025). "Subsequent validation in our database confirmed these meta-analysis results, demonstrating that LINC-PINT downregulation is associated with tumor progression in specific cancers, such as prostate cancer, breast cancer, and lung cancer." (PMID 38553526, 2024). "Elevated levels of LINC-PINT have been associated with the changes of downstream miRNAs, leading to the deceleration of tumor proliferation and invasion in certain cancers, such as lung cancer and bladder cancer." (PMID 38553526, 2024). "Furthermore, decreased expression of LINC-PINT predicts poor prognosis and advanced clinical tumor stages, suggesting that lncRNAs could serve as a diagnostic and prognostic indicator for lung cancer patients." (PMID 35057806, 2022). "In conclusion, we reported that LINC‐PINT affected proliferation, metastasis and invasion in lung cancer via regulating miR‐543 and inducing PTEN." (PMID 31981466, 2020). "These suggested that LINC‐PINT inhibited lung cancer progression via regulating miR‐543 and PTEN in vivo." (PMID 31981466, 2020). "LINC‐PINT affected proliferation, metastasis and invasion in lung cancer via regulating miR‐543 and inducing PTEN." (PMID 31981466, 2020). "In addition, the reduced expression of LINC‐PINT was also observed in lung cancer cells, including A549, H460, H1299, and H1650 cells compared to human lung cell lines WI‐38 and HEL‐1 (F value = 51.01, P < .01)." (PMID 31981466, 2020). "Our study implied that LINC‐PINT could function as a potential biomarker and therapeutic target for lung cancer diagnosis and therapy." (PMID 31981466, 2020). "Hence, in this research, we focused on exploring the interaction between LINC‐PINT and miRNAs in lung cancer cells." (PMID 31981466, 2020). "These manifested that LINC‐PINT repressed lung cancer cell proliferation." (PMID 31981466, 2020). "Meanwhile, LINC‐PINT greatly repressed lung cancer progression in vitro." (PMID 31981466, 2020). "Here, we investigated the effects of LINC‐PINT on lung cancer progression." (PMID 31981466, 2020). "Here, we reported LINC‐PINT was greatly reduced whereas miR‐543 was upregulated in lung cancer." (PMID 31981466, 2020). "Overexpression of LINC‐PINT inhibited miR‐543 expression in lung cancer cells." (PMID 31981466, 2020). "miR‐543 restrained PTEN expression and LINC‐PINT rescued that in lung cancer cells." (PMID 31981466, 2020). "LINC‐PINT was greatly reduced whereas miR‐543 was up‐regulated in lung cancer." (PMID 31981466, 2020). "Collectively, these results show that LINC-PINT, which is downregulated in several types of cancer, included colorectal and lung cancer, contributes to the PRC2-dependent silencing of an invasion gene signature mediated by a sequence element conserved in mammals." (PMID 29078818, 2017). "Finally, xenografts were utilized to confirm the function of LINC‐PINT on lung cancer." (PMID 31981466, 2020). "Thus, LINC‐PINT was potentially a novel therapeutic target for lung cancer patients." (PMID 31981466, 2020). "Moreover, we exhibited that miR‐543 was remarkably increased in lung cancer, which could be regulated by LINC‐PINT negatively." (PMID 31981466, 2020).
breast carcinoma (6 papers, 2018 to 2025). "Moreover, high expression of ACVR2B-AS1, WEE2-AS1, LINC-PINT or HAND2-AS1 was associated with favorable DFS in breast cancer patients in the TCGA cohort." (PMID 30764831, 2019). "C-F Patients with high expression (N = 266) of TSLNRs (ACVR2B-AS1, WEE2-AS1, LINC-PINT and HAND2-AS1) had favorable DFS than those with low expression (N = 266) in breast cancer in TCGA." (PMID 30764831, 2019). "In addition, LINC-PINT suppresses the genesis of non-small cell lung cancer (NSCLC) as the miR-218-5p sponge through MAFG-AS1, and modulates miR-339-5p expression to promote breast cancer (BC) aggressiveness." (PMID 34900992, 2021).
melanoma (6 papers, 2019 to 2022). A malignant, usually aggressive tumor composed of atypical, neoplastic melanocytes. "Here, we identified the tumor-suppressive role of LINC-PINT in melanoma and uncovered the underlying epigenetic regulatory mechanism." (PMID 31921860, 2019). "Therefore, our study elucidates the potential role of LINC-PINT in the development of melanoma and unveils its molecular mechanism underlying tumor progression." (PMID 31921860, 2019). "Our findings elucidated the tumor-suppressive role of LINC-PINT in human melanoma and unveiled its molecular mechanism underlying tumor progression which might thereby suggest a novel therapeutic strategy for melanoma." (PMID 31921860, 2019). "LINC-PINT may serve as a novel diagnostic and therapeutic target for melanoma." (PMID 31921860, 2019). "In the animal xenograft model, LINC-PINT overexpressed melanoma cells represented significant tumor growth inhibition and metastasis reduction effects." (PMID 31921860, 2019). "We utilized the Real-time PCR methodology to determine the expression of LINC-PINT in melanoma cell lines." (PMID 31921860, 2019). "In conclusion, LINC-PINT inhibits the tumorigenicity of melanoma through recruiting EZH2 to the promoter of its target genes, leading to H3K27 trimethylation and epigenetic silencing of target genes." (PMID 31921860, 2019). "LINC-PINT plays a role in suppressing the tumorigenicity of melanoma, which was further determined by xenograft model assay." (PMID 31921860, 2019). "Collectively, these data suggested that LINC-PINT regulated melanoma progression by modulating the expression of a series of cell cycle genes." (PMID 31921860, 2019). "Both 3’-RACE and 5’-RACE results showed that only one band was presented, indicating that there are only one LINC-PINT isoform exists in melanoma cells." (PMID 31921860, 2019). "In summary, we identified an lncRNA, LINC-PINT, and proposed a mechanistic model to elucidate its role in the regulation of melanoma progression through EZH2-mediated epigenetic silencing." (PMID 31921860, 2019). "In this study, it’s our aim to identify the potential regulation role of LINC-PINT in melanoma progression." (PMID 31921860, 2019). "Although the function and structure of LINC-PINT have been studied for more than 4 years, a more comprehensive role of LINC-PINT in regulating the melanoma tumorigenesis still remains to be elucidated." (PMID 31921860, 2019). "For melanoma patients, lower expression of LINC-PINT was associated with poorer overall survival and disease-free survival." (PMID 31921860, 2019). "To evaluate the effect of LINC-PINT on tumorigenesis of melanoma, we used Cell Counting Kit-8 (CCK8) and colony formation assay." (PMID 31921860, 2019). "Through gain- and loss-function experiments in vitro and in vivo, we found that overexpression of LINC-PINT inhibited the progression of human melanoma." (PMID 31921860, 2019). "Results based on the in vivo xenograft model were further consistent with the in vitro findings that LINC-PINT impeded growth and metastasis of melanoma cells." (PMID 31921860, 2019). "CCK8 assay showed that cell proliferation was significantly suppressed in LINC-PINT-overexpressed melanoma cells." (PMID 31921860, 2019). "Here, we revealed a novel transcript of LINC-PINT as a tumor suppressor to inhibit melanoma progression via recruiting EZH2 to the promoter of cell cycle related genes." (PMID 31921860, 2019). "In this manuscript, it is observed that overexpression of LINC-PINT significantly inhibited melanoma proliferation both in vitro and in vivo." (PMID 31921860, 2019). "Additionally, LINC-PINT inhibits the growth and metastasis of melanoma by regulating the epigenetics of target genes, including PCNA, CDK1, CCNA2 and AURKA." (PMID 36601121, 2022).
melanoma (continued). "Strikingly, overexpression of LINC-PINT significantly reduced melanoma cells progression via downregulating the potential target genes CDK1, CCNA2, AURKA, and PCNA through recruiting EZH2 protein, which in turn mediated the trimethylation of H3K27 of promoter regions of target genes." (PMID 31921860, 2019). "Furthermore, total RNAs extracted from melanoma cells (A375) was used to clone the full-length of LINC-PINT transcripts by 5’- and 3’- RACE technologies." (PMID 31921860, 2019). "We also observed that the LINC-PINT-overexpressed melanoma cells formed smaller colonies." (PMID 31921860, 2019). "Moreover, LINC-PINT expression level was also significantly low in melanoma tissues compared with adjacent normal tissues." (PMID 31921860, 2019). "The expression levels of LINC-PINT in melanoma cells were significantly low." (PMID 31921860, 2019). "We detected that LINC-PINT was successfully overexpressed in these melanoma cells by real-time PCR." (PMID 31921860, 2019). "Notably, survival analysis showed that low LINC-PINT expression was prominently correlated with poor overall survival and disease-free survival for melanoma patients." (PMID 31921860, 2019). "In summary, LINC-PINT was expressed at remarkably lower levels in melanoma tissues and cell lines." (PMID 31921860, 2019). "Furthermore, transwell assay showed that LINC-PINT overexpression also inhibited the migration ability of melanoma cells." (PMID 31921860, 2019). "Consistently, the colony formation of melanoma cells was decreased after overexpressing LINC-PINT." (PMID 31921860, 2019). "LINC-PINT was significantly downregulated in melanoma tissues and cell lines." (PMID 31921860, 2019). "We found that LINC-PINT was one of the most downregulated lncRNAs in melanoma cells." (PMID 31921860, 2019). "The results revealed that LINC-PINT overexpression noticeably inhibited melanoma metastasis." (PMID 31921860, 2019). "Thus, cellular fractionation assay was conducted and determined that LINC-PINT distributed mainly in the nucleus of melanoma cells." (PMID 31921860, 2019). "Additionally, recent studies have shown that LINC-PINT plays a vital role in several types of human cancers, melanoma included." (PMID 31921860, 2019). "Although it is reported by a recent study that LINC-PINT is downregulated in melanoma tissues and inhibited cell proliferation through downregulating lncRNA BANCR, whether LINC-PINT has novel functions with diverse mechanism in human melanoma still remains to be identified." (PMID 31921860, 2019). "Our findings indicate that LINC-PINT could be a potential therapeutic target for human melanoma." (PMID 31921860, 2019). "In melanoma cell lines, EZH2 is the only functional protein that binds to LINC-PINT in the nuclei, and LINC-PINT exerts an inhibitory effect on the pathogenesis of melanoma through enriching EZH2 to the promoter of its target genes." (PMID 34257531, 2021). "In this study, we demonstrated that LINC-PINT was an EZH2-binding lncRNA and play an tumor-suppressive role in melanoma progression." (PMID 31921860, 2019). "To comprehensively analyze the tumor-suppressive regulatory effect of LINC-PINT on gene expression, we performed a microarray analysis to profile gene expression in melanoma cells with or without LINC-PINT overexpression." (PMID 31921860, 2019). "Moreover, we performed flow cytometry assay to determine whether LINC-PINT was involved in cell cycle regulation and found that LINC-PINT overexpression induced G0/G1 cell cycle arrest in melanoma cells." (PMID 31921860, 2019). "Thus, we selected melanoma cell lines A375, Mum2B and CRMM1 to test whether LINC-PINT overexpression could alter the tumor behavior." (PMID 31921860, 2019).
thyroid cancer (6 papers, 2022 to 2024). "MiR-767-5p promoted tumor aggressiveness and could be sponged by LINC-PINT in thyroid cancer." (PMID 36147869, 2022). "More importantly, some non-coding RNAs were considered as the known prognosis biomarkers in thyroid cancer, such as let-7a, LINC-PINT, H19, MALAT1 and HOXA-AS2." (PMID 37153003, 2023). "For example, LINC‐PINT modified miR‐767‐5p/TET2 and inhibited malignant behaviour in thyroid cancer." (PMID 34890108, 2022).
pancreatic cancer (5 papers, 2018 to 2025). "Another study reported that LINC-PINT was downregulated in plasma and associated with tumour recurrence in patients with pancreatic cancer." (PMID 36087249, 2022). "LINC-PINT SNP rs6971499 is associated with pancreatic cancer risk in the Caucasian population." (PMID 37553573, 2023). "Linc-PINT downregulation has also been shown in colorectal tumors, in cholangiocarcinoma and in pancreatic cancer." (PMID 29560114, 2018). "For example, LINC-PINT was found to be downregulated in PDAC, and low plasma LINC-PINT expression might serve as a biomarker for early pancreatic cancer detection, whereas low levels of LINC-PINT in tumour tissues correlated with a poor prognosis after pancreatectomy." (PMID 40427100, 2025). "Importantly, LINC-PINT overexpression as well as exogenous TGF-β1 stimulation specifically reduced the proliferation of the pancreatic cancer cell line without affecting the growth of the non-malignant immortalized cells." (PMID 40427100, 2025). "Furthermore, the overexpression of LINC-PINT upregulated TGF-β1 expression in a pancreatic cancer cell line but not in telomerase-immortalized pancreatic ductal cells." (PMID 40427100, 2025).